RNU6-232P (RNA, U6 small nuclear 232, pseudogene)
Gene: Small nuclear RNA gene on chromosome 3 (125,388,934 to 125,388,997, forward strand). Ensembl gene ENSG00000252953.
Homologues: Orthologues: chimpanzee U6 (97% identical), mouse Gm23552 (83% identical), mouse Gm24072 (83% identical), mouse Gm24712 (83% identical), rat LOC120102599 (81% identical), mouse Gm23977 (80% identical), mouse Gm22621 (78% identical). Paralogues in human: RNU6-1248P (92% identical), RNU6-1050P (89% identical), RNU6-1060P (89% identical), RNU6-116P (89% identical), RNU6-1243P (89% identical), RNU6-24P (89% identical), RNU6-748P (89% identical), RNU6-829P (89% identical), RNU6-906P (89% identical), RNU6-949P (89% identical), RNU6-1024P (88% identical), RNU6-1266P (88% identical), and 1286 more.